Y_RNA (Y RNA )
Gene: Miscellaneous RNA gene on chromosome 5 (78,317,036 to 78,317,137, forward strand). Ensembl gene ENSG00000206714.
Homologues: Orthologues: chimpanzee Y_RNA (99% identical), macaque Y_RNA (97% identical), dog Y_RNA (77% identical), tropical clawed frog Y_RNA (69% identical). Paralogues in human: Y_RNA (85% identical), Y_RNA (84% identical), RNY3 (83% identical), Y_RNA (83% identical), Y_RNA (82% identical), RNY3P1 (81% identical), Y_RNA (81% identical), Y_RNA (80% identical), RNY3P11 (79% identical), RNY3P14 (79% identical), Y_RNA (79% identical), RNY3P10 (78% identical), and 93 more.